DIO3 (iodothyronine deiodinase 3)
Diseases named in the same sentence as DIO3 in open-access papers (continued):
Sharing a sentence is not in itself a finding about the gene and the disease.
DIO3 also shares sentences with these, for which no sentence is quoted: lung carcinoma (7 papers); acute promyelocytic leukemia (6); lung adenocarcinoma (5); autoimmune disease (3); Duchenne muscular dystrophy (3); hepatoblastoma (3); hypertrophy (3); muscular dystrophy (3); squamous cell carcinoma (3); alcohol (2); autoimmune disorders (2); breast invasive carcinoma (2); depression (2); experimental autoimmune encephalomyelitis (2); glioblastoma (2); Glucose intolerance (2); leukaemia (2); melanoma (2); Myelodysplasia (2); neuroblastoma (2); preeclampsia (2); prostate carcinoma (2); sarcopenia (2); type 2 diabetes mellitus (2); acute myeloid leukemia (1); adenocarcinoma (1); angiosarcoma (1); aortic stenosis (1); Atrophy (1); autism spectrum disorder (1).
A further 52 diseases each share a sentence with DIO3 in 1 paper.